TERT (telomerase reverse transcriptase)
Diseases named in the same sentence as TERT in open-access papers (continued):
Sharing a sentence is not in itself a finding about the gene and the disease.
melanoma (411 papers, 2007 to 2026). A malignant, usually aggressive tumor composed of atypical, neoplastic melanocytes. "A major molecular feature of melanoma is abnormal telomerase activation; this is most often caused by telomerase reverse transcriptase (TERT) promoter mutations, which occur in 50-82% of cases and are the most common noncoding alteration in this cancer." (PMID 41744838, 2026). "In 2013, two somatic mutations were identified in the promoter region of the TERT gene, which are linked to increased TERT expression in melanoma." (PMID 40361989, 2025). "Grade 3 is marked by sarcoma, carcinoma, or melanoma-like appearances and telomerase reverse transcriptase (TERT) promoter mutations." (PMID 39740420, 2025). "TERT promoter methylation, combined with TERT promoter mutations or without showed reduced recurrence-free survival in adolescent and young adult melanoma patients." (PMID 40361989, 2025). "We found that TERT promotor mutations were associated with any clinical response and local control in both univariate and multivariate analysis in melanoma patients treated with T-VEC." (PMID 39422848, 2025). "TERT promoter mutations were most frequent in bladder-urothelial cancer (75.3%), while skin cancer (60.6%), melanoma (58.2%), and liver cancer (52.8%) also had expectedly high frequencies." (PMID 40711866, 2025). "A subsequent large population-based study identified this rare TERT promoter mutation in another melanoma family confirming its high penetrance, its association with early onset melanoma, and highlighting an increased risk of developing other cancers." (PMID 40869905, 2025). "Variants in the TERT gene are responsible for approximately 1% of familial melanoma cases and increase the risk of familial liver diseases, idiopathic pulmonary fibrosis, and lung cancer." (PMID 40558591, 2025). "In melanoma, the aberrant overexpression of TERT is predominantly driven by three mechanisms: promoter mutations, TERT amplification, and enhancer hijacking." (PMID 39871386, 2025). "Class II and III driven MAP2K1-mutated melanomas have significant metastatic potential, particularly when accompanied by TERT-p mutations." (PMID 40107205, 2025). "Genomic mutations in TERT have been experimentally validated as drivers of oncogenesis, particularly in melanoma." (PMID 40737104, 2025). "Up to 78% of melanomas also carry a TERT promoter mutation, which increases telomerase activity and allows cells to maintain telomeric elongation, resulting in prolonged survival and abnormal proliferation." (PMID 41295253, 2025). "In contract, the adoption of ddPCR for detecting common melanoma mutations including BRAF, NRAS, KIT, and TERT significantly improved sensitivity, allowing ctDNA to be distinguished from total cfDNA in approximately 80% of melanoma patients." (PMID 39859576, 2025). "In this study, plasma-derived levels of ctDNA from assays for BRAF and NRAS driver mutations as well as TERT promotor mutations were analyzed in patients with advanced melanoma." (PMID 40002300, 2025). "The heterogeneous pattern was associated with a higher Breslow index, fast-growing melanomas, higher mitotic rate, and TERT promoter mutations." (PMID 40361989, 2025). "Other high- and moderate-penetrance genes—such as BAP1, POT1, BRCA2, and TERT—were also included, reflecting an expanded institutional approach to hereditary melanoma risk assessment." (PMID 40863406, 2025). "Skin melanomas showed a higher frequency of specific gene alterations such as CDKN2A deletion (P < .05), BRAF single-nucleotide variants (SNVs; P < .01), and TERT promoter variants (P < .01) than mucosal melanomas." (PMID 39823560, 2025).
melanoma (continued). "This is significant because TERT promoter mutations are present in 30–85% of melanomas, including up to half of BRAF wt cases." (PMID 39859576, 2025). "Melanomas arising in patients with TERT promoter mutations are frequently associated with increased Breslow thickness and a correspondingly worse prognosis." (PMID 39871386, 2025). "With the exception of one melanocytoma, all tumours with TERT-p mutations were classified as melanoma." (PMID 40107205, 2025). "This work describes the experience using T-VEC in melanoma at a single institution and highlights the presence of TERT promotor mutations as a possible driver of clinical response." (PMID 39422848, 2025). "Germline variants in CDKN2A, CDK4, BAP1, POT1, ACD, TERF2IP, and TERT have been identified as high-penetrance variants associated with melanoma development." (PMID 40429816, 2025). "TERT promoter mutations in melanomas were linked to decreased disease-specific and overall survival." (PMID 40361989, 2025). "Mutations in the promoter region of the TERT gene tend to arise in the initial stages of melanoma development." (PMID 40361989, 2025). "Molecular profiling confirmed the diagnosis of melanoma and identified mutations in the TERT promoter, NRAS, NF1, PBRM1, FAT1, and ATM genes." (PMID 40125165, 2025). "TERT promotor mutations have been negatively correlated with tumor clinicopathological features in other tumors such as melanoma, bladder carcinoma, gliomos, and thyroid carcinoma." (PMID 40307280, 2025). "TPP1 promoter mutations work in conjunction with TERT activation to promote telomere maintenance and cellular immortalisation in melanoma." (PMID 40361989, 2025). "For example, BCAN is significantly differentially expressed in IFN-treated melanoma, and promoter mutations of TERT in melanoma and COL1A1 promote melanoma invasion, among others." (PMID 40350499, 2025). "Mutations in the TERT promoter, specifically C250T and C228T, which appear in 30–85% of melanoma patients, offer an alternative marker for ctDNA monitoring." (PMID 39859576, 2025). "Aggressive behaviour of Class II or III MAP2K1-driven tumours is likely stimulated by additional oncogenic alterations, as all these melanomas also harboured TERT-p mutations." (PMID 40107205, 2025). "TERT promotor mutations have been reported in approximately 22%-68% of melanoma cases and have been shown to be an adverse prognostic indicator." (PMID 39974235, 2025). "If the genetic mutational burden increases, with TERT promoter mutations (TERT gene encoding telomerase reverse transcription), the benign melanocytic lesions transform into intermediate lesions and melanoma in situ." (PMID 39063046, 2024). "The main difference is that DPN-like melanomas often harbor additional genetic alterations, including TERT-p mutations and inactivation of CDKN2A." (PMID 38247727, 2024). "Telomerase reverse transcriptase (TERT) mutations are key players in melanoma genesis and progression." (PMID 38667446, 2024). "In melanoma, TERT promoter mutations, MITF, and CTNNB1 were amongst the genes enriched in metastatic vs. primary Class 1 BRAF mutant tumors." (PMID 38275886, 2024). "Telomerase reverse transcriptase (TERT) mutations are key players in the genesis and progression of melanoma." (PMID 39199954, 2024). "TERT promoter mutations are commonly found in malignant melanomas and recently have been related to advanced stage and decreased survival." (PMID 39258061, 2024). "Although our patient did not have BRAF mutation, which is the most common mutation identified in malignant melanoma, he was found to have TERT mutation." (PMID 39258061, 2024). "Previous studies have reported that 37.9 % of primary melanomas harbored a TERT mutation, whereas they showed that, a higher percentage of TERT mutations (74 %) was identified in the metastases of these same melanomas." (PMID 38158497, 2024).
melanoma (continued). "The authors also noted better overall survival outcomes with anti-CTLA4 therapy, among patients with melanoma harboring TERT promoter mutations." (PMID 37462445, 2024). "Telomerase reverse transcriptase (TERT) mutations play an important role in the development of melanoma." (PMID 38469235, 2024). "In the subsequent step, called the expansion phase, certain melanocytic nevi advance into intermediate lesions that develop TERT promoter mutations and eventually develop into melanoma in situ." (PMID 39195270, 2024). "For example, reverting the TERT promoter mutation -146 C > T in melanoma cells led to significant growth inhibition both in vitro and in vivo, suggesting potential therapeutic strategies for targeting these mutations." (PMID 39200315, 2024). "One of the fundamental genetic alterations in melanoma is the presence of mutations in the promoter region of the TERT gene, TERTp mutations–C228T and C250T." (PMID 39078811, 2024). "We have succeeded in determining the most common mutations in the BRAF, NRAS, and TERT genes that cause melanoma." (PMID 39195270, 2024). "The prevalence of TERT promoter mutations in melanoma varies between 29% and 71%.24,25 In our cohort, 43% of 2243 melanoma cases harbored TERT promoter mutations." (PMID 37462445, 2024). "In a comprehensive literature review and meta-analysis, data from 19 independent studies showed that TERT-mutated melanoma patients had a significantly worse OS as compared with wild-type ones." (PMID 39530091, 2024). "Mutations in the promoter region of TERT are related to reduced disease-free survival, increased tumor recurrence, and an increased rate of metastasis in melanoma." (PMID 38667446, 2024). "TERT promoter mutations are the most common type of TERT alterations in melanoma, accounting for up to 65% of cutaneous melanoma." (PMID 38667446, 2024). "Mutations in the TERT (telomerase reverse transcriptase) promoter are likely the most common mutations in melanoma and have been linked to more aggressive melanomas and worse outcomes, indicating that these changes represent an adverse prognostic factor." (PMID 38534309, 2024). "Examining the distribution of TERT promoter mutations by race, White patients with melanoma harbored more TERT promoter mutations than Asian and Black patients (OR = 25.83; 95%CI, 6.84-217.42; P < .001)." (PMID 37462445, 2024). "We observed a high frequency of TERT promoter mutations in AYA melanomas that showed a trend of co-occurrence with BRAF mutations, similar to findings in older adult patients which potentially suggests an intrinsic pathway of immunosuppression." (PMID 38589406, 2024). "For example, these approaches have been employed to create mice with mutations in the TERT promoter region, providing insights into non-coding TERT mutations detected in melanomas." (PMID 38902506, 2024). "TERT promoter mutations are common in melanoma and are associated with aggressive tumors and worse outcomes." (PMID 38534309, 2024). "Telomerase reverse transcriptase is traditionally associated with its role in telomere lengthening and chromosomal stability, but its expression in melanoma cells has broader implications for cancer progression." (PMID 39078811, 2024). "Telomere instabilility is a key feature of melanoma given the high frequency of somatic TERT promoter variants identified in sporadic melanoma, however, TERT germline variants are only detected rarely in FM." (PMID 39247651, 2024). "Mutations in the promoter region of the TERT gene, which encodes the telomerase reverse transcriptase, are common in melanoma and associated with increased telomerase activity, promoting cellular immortality." (PMID 39200315, 2024). "Recurrent mutations in the promoter of the TERT gene were initially detected in melanoma and then in various additional cancer types." (PMID 38667446, 2024).
melanoma (continued). "For example, White patients with melanoma (44%, n = 964/2176) harbored more TERT promoter mutations compared to Asian and Black patients (3%, n = 2/67) (OR = 25.83; 95%CI, 6.84-217.42; Q < .001)." (PMID 37462445, 2024). "TERT mutation can be used to identify melanoma patients with poor prognosis, including relapsing, disease, and death." (PMID 37239381, 2023). "It has been proposed that the chronological order of the mutations in BRAFV600E and TERT has an influence on the model of melanoma evolution." (PMID 36834954, 2023). "TERT is mutated in many solid tumors, including central nervous system malignancies, thyroid cancer, and melanoma." (PMID 37575241, 2023). "For example, TERT promoter mutations were one of the earliest highly recurrent non-coding mutations identified in melanoma and are remarkable due to both a strong activating effect and prevalence in multiple cancers." (PMID 38030698, 2023). "Core promoter mutation in TERT in melanoma is one of the few examples of core promoter mutation and diseases." (PMID 36307127, 2023). "TERT promoter mutations are the most frequent mutations in melanoma, co-occur regularly with BRAF alterations and are associated with a poorer prognosis." (PMID 37296851, 2023). "The co-occurrence of BRAF or NRAS mutations with TERT promoter mutations was also prognostic for poor disease-free survival in multivariate analyses in primary melanoma." (PMID 37418389, 2023). "Subsequently, a series of studies have shown that hypermethylation of TERT promoter is associated with poor prognosis in tumors such as melanoma, gastric cancer, bladder cancer, prostate cancer and thyroid cancer." (PMID 37575241, 2023). "TERT promoter mutations are the main mechanism for the continuous upregulation of telomerase in melanoma and co-occur frequently with BRAF alterations." (PMID 37296851, 2023). "Mutations in the promoter of TERT are probably the most frequent mutation in melanoma and have been collectively associated with more aggressive melanomas and poorer outcomes, suggesting that these alterations were a poor prognostic factor." (PMID 37296851, 2023). "Benign melanocytic nevi harbour trunk nucleotide changes, such as BRAF and NRAS mutations, before progressing to melanoma and accumulate nucleotide changes in TERT promoter at the transition from benign nevus to melanoma in situ." (PMID 38033865, 2023). "First identified in melanoma, TERT mutations have become increasingly identified as one of the most common noncoding mutations in all cancers." (PMID 38076247, 2023). "In a cohort of V600E-BRAF-mutated melanoma patients, we showed that the TERT promoter mutation status and TERT expression tended to be associated with response to BRAF and MEK inhibitors." (PMID 37296851, 2023). "Mutation in the TERT core promoter causes TERT overexpression in several types of cancer including melanoma and bladder cancer (Most of the gene expression studies in diseases focused on measuring the changes at mRNA or protein levels)." (PMID 36307127, 2023). "Non-coding mutations in the TERT promoter are well-established driver mutations in melanoma that create functional ETS binding sites." (PMID 37169747, 2023). "Multiple studies have reported a high prevalence of TERT promoter mutations in melanoma, particularly in cases with aggressive clinical features and poor prognosis." (PMID 37504268, 2023). "In accordance, we found in our cohort of BRAF-mutated patients that most melanomas (85%) presented a mutation in the TERT promoter, the most frequent being −124C > T (50%) followed by −146C > T (28%) and by −138/−139CC > TT (7%)." (PMID 37296851, 2023). "Studies have also explored the relationship between TERT promoter mutations and other common genetic alterations in melanoma, such as BRAF and NRAS mutations." (PMID 37504268, 2023).
melanoma (continued). "The highest frequencies of TERT promoter mutations have been reported in melanoma, bladder cancer, urothelial carcinoma, CNS tumors, hepatocellular carcinoma, thyroid cancer, basal cell carcinoma, and cutaneous squamous cell carcinoma." (PMID 36979671, 2023). "Hep-G2 harbors an activating TERT promoter mutation that leads to monoallelic overexpression equaling biallelic expression in other cancer entities such as melanoma." (PMID 37993930, 2023). "Within the four major genetic subtypes of cutaneous melanomas, TERT promoter mutation is observed in 75% of tumors with BRAF mutation but only observed in 6.7% of TWT melanomas." (PMID 37239381, 2023). "One of the most common genetic alterations in the TERT gene in melanoma is the presence of mutations in the TERT promoter region." (PMID 37504268, 2023). "The close connection between MAPK kinase activation and TERT expression led to investigating the correlation between TERT promoter mutations and resistance to targeted therapies in melanoma." (PMID 37296851, 2023). "Mutations occurring in the TERT promoter are one of the earliest secondary changes that occur in approximately 75% of melanomas." (PMID 37174106, 2023). "Melanomas with hotspot mutations carried TERT promoter mutations more often than triple wild-type melanomas (odds ratios >20)." (PMID 37418389, 2023). "Of note, BRAF variations coexist with TERT promoter mutations both in melanoma and in thyroid cancer." (PMID 38033865, 2023). "As the mitogen-activated protein kinase (BRAF-MAPK) signaling pathway is frequently activated in melanoma, we analyzed TERT in melanoma subtypes with hotspot mutations in BRAF, RAS (NRAS, KRAS, HRAS) and NF1 genes in the SKCM cohort." (PMID 37418389, 2023). "Tumor samples from 48 patients with advanced BRAF-mutated melanoma were collected before treatment and analyzed for TERT promoter mutation status." (PMID 37296851, 2023). "These mutations have even a prognostic value, since TERT promoter mutations have been identified as independent prognostic markers in melanoma." (PMID 37504268, 2023). "Two major hotspot TERT promoter mutations (C228T and C250T) have been reported in different malignancies such as melanoma, genitourinary cancers, CNS tumors, hepatocellular carcinoma, thyroid cancers, sarcomas, and HNCs." (PMID 36979671, 2023). "To further understand the effect of TERT overexpression on resistance, we overexpressed TERT in a melanoma cell line expressing a low level of TERT and showed that it was associated with increased resistance to BRAF and MEK inhibition." (PMID 37296851, 2023). "The coexistence of mutations in BRAF and NRAS genes as well as in TERT promoter are associated with poor disease-free survival in melanoma patients." (PMID 38033865, 2023). "Our examination of clinical variables in association with TERT promoter mutations and expression was based on the two largest melanoma cohorts, the SKCM and Liu cohorts." (PMID 37418389, 2023). "Melanoma is heavily burdened by non-coding variants, representing over 99% of total genetic variation, including the well-characterized TERT promoter mutation." (PMID 38030698, 2023). "To study the effect of TERT inhibition on BRAF-mutated melanoma cells in culture, we treated sensitive and resistant cells with 6-thio-dG alone or in combination with vemurafenib and analyzed the effect on cellular proliferation." (PMID 37296851, 2023). "Initially found in melanoma and thyroid cancers, recurrent TERT-activating promotor mutations were then described in numerous cancers, including adult GBMs and anaplastic oligodendrogliomas." (PMID 36831610, 2023). "In our cohort of BRAF-mutated melanoma patients, we showed that TERT promoter mutation status and TERT expression tended to be associated with the response to BRAF and MEK inhibitors." (PMID 37296851, 2023).